CTLA4 (cytotoxic T-lymphocyte associated protein 4)
Diseases named in the same sentence as CTLA4 in open-access papers (continued):
Sharing a sentence is not in itself a finding about the gene and the disease.
osteosarcoma (continued). "A phase I trial of the anti-CTLA-4 antibody ipilimumab in heavily pretreated paediatric patients with relapsed or refractory disease yielded stable disease in two of the eight osteosarcoma patients involved in the trial, suggesting moderate activity." (PMID 32961800, 2020). "All of the osteosarcoma and rhabdomyosarcoma cell lines were positive for CTLA-4 expression with osteosarcoma showing higher staining intensity." (PMID 33207697, 2020). "Combination treatment with PD-L1 and CTLA-4 antibodies resulted in complete control of metastatic osteosarcoma in 50% of mice and drastically improved the long-term disease-free survival to 60% compared to 0% observed in mice receiving anti-PD-L1 monotherapy." (PMID 33207697, 2020). "Based on a study of immune checkpoints in patients with osteosarcoma, PD-1, PD-L1, and CTLA-4 influence osteosarcoma progression." (PMID 30693030, 2019). "In conclusion, our study demonstrated that carbon ion irradiation combined with anti-PD-L1 and anti-CTLA4 therapy enhanced antitumor immunity and the inhibitory effect against tumor growth in the primary tumor and distant metastases in osteosarcoma." (PMID 30774761, 2019). "For example, in a C3H murine osteosarcoma model, tumor lysate-pulsed DCs with CTLA-4 blockade prevented lung tumor metastasis." (PMID 31156651, 2019). "In a preclinical study, co-inhibition of CTLA-4 and PD-L1 resulted in complete control of metastatic osteosarcoma." (PMID 31156651, 2019). "In a panel of 34 adult and pediatric tumor cell lines, including osteosarcoma, rhabdomyosarcoma, and neuroblastoma, CTLA-4 expression was found at different densities on 88% of the cell lines examined, with higher intensity of staining in osteosarcoma." (PMID 31847387, 2019). "Kawano reported the effect of combination treatment with tumor lysate-pulsed DCs and an anti-cytotoxic T lymphocyte antigen-4 (CTLA-4) antibody in a mouse model of osteosarcoma." (PMID 30693030, 2019). "Here, we evaluated the efficacy of anti-PD-L1 and anti-CTLA-4 antibodies with X-ray irradiation in both local and distant effects against osteosarcoma." (PMID 29253865, 2017). "The patient with osteosarcoma received anti-CTLA-4 and radiation; the patients with DDLS received anti-PD-1 or anti-PD-L1; the patients with LMS received anti-CTLA-4 or anti-PD-1." (PMID 29254498, 2017). "In a separate article, Lussier and colleagues demonstrate that T cells infiltrating osteosarcoma tumors upregulate CTLA-4, another receptor involved in decreasing activation of cytotoxic T-cells." (PMID 27313973, 2016). "Combining anti-CTLA-4 antibody and tumor lysate-pulsed DCs can promote antitumor reaction in murine osteosarcomas." (PMID 27683579, 2016). "Based on these findings osteosarcoma bearing mice were treated with antibodies against both PD-L1 and CTLA-4." (PMID 27313973, 2016). "Combination of α-CTLA-4 and α-PD-L1 mAb treatment resulted in complete control of metastatic osteosarcoma tumors with long-term disease-free survival in roughly 60% of α-CTLA-4 + α-PD-L1 mAb treated mice." (PMID 25992292, 2015). "Mice previously treated with α-CTLA-4 and α-PD-L1 mAb and that had previously controlled metastatic osteosarcoma were challenged with 106 K7M2 cells at 100 days post-initial inoculation, a time when neither therapeutic antibody should be present in these mice." (PMID 25992292, 2015). "Additionally, osteosarcoma cells exploit immune checkpoint pathways, such as PD-1/PD-L1, CTLA-4, lymphocyte activation gene-3(LAG-3), and T cell immunoglobulin and mucin domain-containing protein 3(TIM-3), to evade immune surveillance." (PMID 40170852, 2025). "Among immunotherapeutic strategies, immune checkpoint blockade (ICB) targeting the programmed cell death protein 1 (PD-1)/PD-1 ligand (PD-L1) and cytotoxic T-lymphocyte antigen 4 (CTLA-4)pathways has demonstrated clinical success in several cancers and is now being actively explored in osteosarcoma." (PMID 40170852, 2025).
osteosarcoma (continued). "Similarly, when osteosarcoma cells were incubated with recombinant B7-1 or B7-2 ligands, CTLA-4 directed caspase-dependent apoptosis in these cells, further exploring its sensitivity to be targeted by anti-cancer agents." (PMID 37605389, 2024). "Furthermore, the efficacy of anti-CTLA-4 immunotherapy in osteosarcoma clinical treatment remains ambiguous." (PMID 38915446, 2024). "Although the combination of two ICIs acting through different mechanisms, such as anti-CTLA4 and anti-PD-1, has shown synergy in preclinical models of osteosarcoma as well as in those of melanoma, such combinations have had mixed response so far in bone sarcomas." (PMID 37569894, 2023). "Notably, strategies aimed at the novel targets PD-1 and CTLA-4 represent a new era of antitumor immunotherapy and improve the potential for osteosarcoma therapy." (PMID 36849442, 2023). "The expression of immune checkpoint molecules such as PD-L1 and CTLA-4 is also high in osteosarcoma tissues, which may be involved in the mechanism of anti-tumor immune escape." (PMID 37497349, 2023). "Therefore, we concluded that CD8 activation by T-cells was directly prevented by the CD86/CTLA4 coinhibitory signal and was indirectly inhibited by Tregs in osteosarcoma." (PMID 35463956, 2022). "Further, LM8 osteosarcoma cells bearing mice irradiated with either carbon ions or x-rays along with PD-1 and CTLA-4 inhibitors experienced abrogated growth of the abscopal tumors, which was mediated by increased CD8 + cells unlike mice treated with RT or ICI alone." (PMID 34980128, 2022). "Therefore, the CTLA4 co-inhibitory signal mainly inhibits the activity of CD8 T-cells in osteosarcoma." (PMID 35463956, 2022). "Moreover, we see that gene expression value of CTLA4 is significantly correlated with CD8 T cells in osteosarcoma tumors." (PMID 33757216, 2021). "Therefore, it is probable that treatments that attempt to increase this rate of cytotoxic cells attacking tumor cells, such as PD-1 or CTLA-4 inhibitors, would work well for osteosarcoma." (PMID 34068946, 2021). "In addition, specific immune checkpoint inhibitors are being explored as new immunotherapeutic strategies for osteosarcoma, such as CTLA-4, LAG3, TIGIT, and PD-1/L1 (Wang S.-D." (PMID 34899864, 2021). "Previous experiments using this K7M2 metastatic osteosarcoma model have shown that low-dose anti-CTLA-4 can synergize in combination with anti-PD-L1 therapy to confer some level of durable tumor-free survival, but it is completely ineffective as a monotherapy in this model." (PMID 34553039, 2021). "Cluster 1 also has the highest expression of CTLA4 gene (Figure 5A3, B3) that encodes Cytotoxic T-Lymphocyte Associated Protein 4 (CTLA4), which is a member of immunoglobulin superfamily and has been found to significantly associate with the risk of osteosarcoma." (PMID 33757216, 2021). "Collectively, this suggests that osteosarcoma may utilize PD-L1, PD-L2, B7-H3, and CTLA-4 to counteract immune recognition." (PMID 32961800, 2020). "On the basis of the recent evidence that the induction of type-I interferons is associated with radiation-induced antitumor immunity, we show that a high, but not intermediate, dose of local irradiation is necessary to exert the maximum efficacy of the anti-CTLA-4 antibody (C4) for osteosarcoma." (PMID 32545427, 2020). "Another study looking at peripheral blood samples from 19 paediatric patients (11 osteosarcoma patients and eight Ewing sarcoma patients) reported significantly increased CTLA-4 expression on both CD4+ (38% vs. 16%) and CD8+ (37% vs. 12%) T cells compared to healthy donors." (PMID 33207697, 2020). "In addition, 20 pediatric patients, 11 with osteosarcoma and 9 with Ewing sarcoma, had significantly increased expression of CTLA-4 on both CD4+ and CD8+ T cells obtained from peripheral blood samples compared to healthy controls." (PMID 31847387, 2019).
osteosarcoma (continued). "The purpose of this study was to investigate whether X-ray irradiation combined with anti-PD-L1 and anti-CTLA-4 antibodies (P1C4) provides a higher probability of this distant effect as well as enhanced local antitumor efficacy for osteosarcoma." (PMID 29253865, 2017). "In conclusion, we found that high dose radiation was necessary in anti-PD-L1 and anti-CTLA-4 therapy for local control as well as inhibition of distant metastasis in this mouse model of osteosarcoma, and that this treatment leads to the longest overall survival." (PMID 29253865, 2017). "We next asked whether immunity to metastatic osteosarcoma in combination α-CTLA-4/α-PD-L1 mAb treated mice that controlled initial K7M2 tumors correlated with retention or improved T cell function." (PMID 25992292, 2015). "In this study, we noted a higher expression level of the ICGs (CTLA4, CD274, PDCD1C, HAVCR2, and LAG3) in the osteosarcoma patients categorized into the low‐risk group, which suggested that these patients could gain more benefits from the immune checkpoint blockade therapy." (PMID 36129020, 2023). "Therefore, we evaluated the efficacy of bempegaldesleukin (BEMPEG; NKTR‐214), a first‐in‐class CD122‐preferential IL‐2 pathway agonist, alone and in combination with anti‐PD‐1 or anti‐CTLA‐4 immune checkpoint inhibitors in metastatic and orthotopic murine models of osteosarcoma." (PMID 33152115, 2021). "Recently, our group reported that dual immune checkpoint blockade of anti-PD-L1 (P1) and anti-CTLA-4 (C4) antibodies combined with single delivery of 10 Gy X-ray irradiation enhanced the systemic antitumor response both at local and distant sites in murine osteosarcoma." (PMID 32545427, 2020). "Importantly, a phase I clinical trial is currently underway to test the safety and efficacy of PD-1 antibody alone, or in combination with CTLA-4 antibody for the treatment of children, adolescents and young adults with osteosarcoma and other solid tumors (NCT02304458)." (PMID 27313973, 2016). "In the osteosarcoma TIME, this occurs through the interaction of CD86 molecules on MDSCs, which serve as ligands for CTLA4 on Tregs." (PMID 39359731, 2024). "Ipilimumab, a CTLA-4 inhibitor, is currently FDA approved for use in advanced melanoma, and its application in the treatment of osteosarcoma is currently under investigation." (PMID 39417976, 2024). "The study of the heterogeneity and immunosuppressive function of Tregs in naïve primary osteosarcoma demonstrated greater Treg infiltration than in normal bone, with a positive expression of FOXP3, CD4, CTLA-4, and TIGIT in Tregs." (PMID 39359731, 2024). "In summary, blocking CD86/CTLA4 signaling and promoting CD86/CD28 signaling are potential strategies for osteosarcoma immunotherapy." (PMID 35463956, 2022). "In this study, CD86 expression was significantly correlated with CTLA4 and CD28 expression in osteosarcoma." (PMID 35463956, 2022). "In our study, murine models of primary and metastatic osteosarcoma were used to study the therapeutic efficacy of BEMPEG both as a monotherapy and in combination with inhibitors of the immune checkpoints PD‐1 and CTLA‐4." (PMID 33152115, 2021). "This study found that macrophage M1 was positively correlated with immune checkpoints PDCD1, CD274 (PD-L1), PDCD1LG2, CTLA4, and TIGIT, suggesting the opportunity of ICBs therapy in osteosarcoma patients with high infiltrating macrophage M1." (PMID 34335756, 2021). "In this K7M2 metastatic osteosarcoma model, the authors show that α‐PD‐L1 mAb‐treated mice demonstrated an adaptive resistance mechanism in the microenvironment where the tumor or tumor microenvironment may be using CTLA‐4 ligation as an alternative pathway to escape immune destruction." (PMID 31376208, 2019). "CTLA-4 negatively regulates T cell function, and blocking CTLA-4 can reactivate T cells and enhance the efficacy of osteosarcoma vaccines." (PMID 31156651, 2019).
osteosarcoma (continued). "Nivolumab, a PD-L1 inhibitor, with or without the CTLA-4 inhibitor ipilimumab, proved ineffective in osteosarcoma, Ewing sarcoma, synovial sarcoma and DSRCT in the ADVL1412 trial." (PMID 40983796, 2025). "CTLA-4, a CD28 homolog, binds B7 ligands, enabling immune escape, observed in osteosarcoma." (PMID 41383602, 2025). "In an implanted mouse model of metastatic osteosarcoma, treatment with anti-PD-L1 antibody reduced the expression of PD-L1, increased the expression of CD80/CD86 in tumor cells, and increased the expression of CTLA-4 in tumor-infiltrating CD8+ T cells." (PMID 38542199, 2024). "Thus, blocking CD86/CTLA4 signaling and promoting CD86/CD28 signaling are potential strategies for osteosarcoma immunotherapy." (PMID 35463956, 2022). "It was shown that combining anti-CTLA-4 and anti-PD-L1 antibodies (P1C4) with irradiation would enable exerting higher distant effects as well as providing greater local antitumor efficiency for osteosarcoma." (PMID 35145371, 2022). "In addition, it enhanced therapeutic activity of anti‐CTLA‐4 and anti‐PD‐1 checkpoint blockade in the DLM8 subcutaneous murine osteosarcoma model." (PMID 33152115, 2021). "Though the exact function of expression of CTLA-4 on tumor cells is unknown, incubating the cells with CTLA-4 ligands CD80 or CD86 induced apoptosis in human osteosarcoma cell line HOS cells through caspase-3 and caspase-8 activation." (PMID 33823818, 2021). "For example, we reported the phenomenon of tumor infiltrating Treg decreasing after administering anti-PD-1 antibody in an osteosarcoma cell line transplanted mouse model and considered it to be the result of ADCC with Treg expressing PD-1, as the same as the anti-CTLA4 antibody." (PMID 32664248, 2020). "Furthermore, several immune molecules, such as cytotoxic T cell lymphocyte antigen 4 (CTLA4) and CD40 (TNF receptor superfamily 5), have been targeted clinically in osteosarcoma." (PMID 29720180, 2018). "Similarly, tremelimumab, another CTLA-4 inhibitor, has been tested in combination with PD-L1 inhibitors, but no significant survival benefit has been observed in osteosarcoma to date." (PMID 40170852, 2025). "Relatively low expression levels of CTLA4, HAVCR2, LAG3, and PDCD1LG2 can be observed in the group of patients with metastasis (p < 0.05), which may indicate and predict a poor prognosis in patients with osteosarcoma." (PMID 38256356, 2024). "Moreover, CD86 expression depended on its receptors, CTLA4 and CD28, in osteosarcoma." (PMID 35463956, 2022). "Interestingly, CTLA-4 expression was detected in osteosarcoma and breast tumor tissues by immunohistochemistry, whereas no or weak CTLA-4 staining was observed in non-malignant breast tissue adjacent to tumors." (PMID 34298809, 2021). "In an implantable murine model of metastatic osteosarcoma, treatment with anti-PD-L1 antibody resulted in downregulation of PD-L1 expression and upregulation of CD80/CD86 expression on tumor cells, as well as upregulation of CTLA-4 on tumor infiltrating CD8+ T cells." (PMID 31847387, 2019). "Furthermore, combination immunotherapy using anti-CTLA-4 and anti-PD-L1 antibodies improved overall survival in a mouse model of osteosarcoma, whereas no benefit was observed upon treatment with an anti-CTLA-4 antibody alone." (PMID 30693030, 2019). "We therefore hypothesized that the combination of anti-PD-L1 and anti-CTLA-4 antibodies, having non-redundant mechanisms for antitumor immune systems, with X-ray irradiation would provide a higher probability of the abscopal effect for osteosarcoma, which is known as an X-ray-resistant neoplasm." (PMID 29253865, 2017).
viral infection (67 papers, 2009 to 2025). "The overexpressions of PD-1 and CTLA-4 in patients with viral infection have been shown to associate with functional impairment of virus-specific T cells." (PMID 28703774, 2017). "Among the overrepresented T-cell-receptor signaling genes, PD-1 (encoded by PDCD1) and CTLA-4 are important inhibitory receptors that are involved in T-cell exhaustion, which is commonly associated with persistent viral infections." (PMID 27643611, 2016). "The genotype distribution of the CTLA4 polymorphisms in patients with viral infection and non-viral infection." (PMID 24015180, 2013). "HPV is also one of the risk factors of HNSC 17-18, and viral infection might recruit immune effector cells and upregulate PD-1 and cytotoxic T-lymphocyte associated protein 4 (CTLA-4) immunosuppressive pathways." (PMID 36605482, 2023). "This new result may indicate a relationship between CTLA-4 haploinsufficient NK cells with high susceptibility to viral infections in affected patients and heterozygous germline mutations in CTLA-4." (PMID 32640575, 2020). "This evolutionary role may rather be with viral infections including hepatitis B, which was found to be controlled more effectively by carriers of the CTLA4 +6230G allele than by those carrying the +6230A/A genotype." (PMID 19609446, 2009). "During chronic viral infections, the immune response can be hindered by immune exhaustion, characterized by the increased expression of inhibitory receptors on lymphocytes, such as cytotoxic T-lymphocyte-associated protein 4 (CTLA4), programmed death-1 (PD-1), and programmed death-ligand 1 (PD-L1)." (PMID 40416970, 2025). "In chronic viral hepatitis, the extended upregulation of PD-1 and CTLA-4 is associated with T-cell exhaustion and persistent viral infection, suggesting that the expressions of immune inhibitory factors are positively associated with the chronicity of viral disease." (PMID 31312140, 2019). "In chronic viral hepatitis, the extended upregulations of PD-1 and CTLA-4 are associated with T cell exhaustion and persistent viral infection, suggesting positive correlations between expression of immune inhibitory factors and the chronicity of viral disease." (PMID 28703774, 2017). "According to studies, the inhibition of CTLA-4 during viral infection or model antigen vaccination enhanced the growth of germinal center B-cells." (PMID 38180994, 2024). "In summary, the CTLA-4/B7 pathways play a pivotal role in COVID-19 infection, underscoring the need for strategies to combat this viral infection more effectively." (PMID 38180994, 2024). "Viral infections have been shown to elevate the expression of immune checkpoint molecules such as CTLA-4 and PD-L1." (PMID 39205202, 2024). "Exhaustion is a fundamental event in many viral infections, and PD-1, PD-L1, and CTLA4 transcript levels are markers of T cell exhaustion." (PMID 38376148, 2024). "CD4cyt are expanded in patients with heterozygous CTLA4 mutations, and the cytotoxicity of CD4+ T cells is increased in cancer patients after ICI therapy and in a mouse model of acute viral infection after CTLA4 blockade." (PMID 37161048, 2023). "CD86, a critical costimulatory molecule and ligand for CD28 and CTLA-4, is upregulated on monocytes and DCs upon virus infection in vitro and in vivo." (PMID 36752598, 2023). "In contrast, the exhausted genes were up‐regulated after viral infection (e.g. Havcr2, Lag3, Cd96 and Ctla4)." (PMID 35051311, 2022). "Studies on chronic viral infection and in vitro blockade showed CTLA4 contribute to the impaired immune response, induction of T cell exhaustion and the failure of immunological control of the persisting pathogens by pathogen-specific T cells." (PMID 35701741, 2022). "The restoration of effector functions in exhausted T cells can lead to control of chronic viral infection as observed after anti-PD-1 and anti-CTLA-4 treatment." (PMID 35774790, 2022).